TNF (tumor necrosis factor)
Diseases named in the same sentence as TNF in open-access papers (continued):
Sharing a sentence is not in itself a finding about the gene and the disease.
Sepsis (continued). "Patients with sepsis frequently have elevated levels of IL-8, C5a, and TNFα in their blood." (PMID 30931316, 2019). "As an example, interleukin (IL)-6 expression is strongly induced by time, intensity and type of muscle contractions-dependently as well as in sepsis (various origin) but, in the latter case, it is driven by the previous increase in another cytokine, the tumor necrosis factor (TNF)-α." (PMID 30792697, 2019). "Overexpressed miR-107 causes TNF-α secretion through regulating dual-specificity phosphatase 7(DUSP7) in circulating endothelial cells, which may lead to tubular cell damage in sepsis-induced AKI." (PMID 31658856, 2019). "Although KEGG showed inflammatory bowel disease in the E. coli group, the KEGG pathway analysis showed that these DEGs were mainly involved in the tumor necrosis factor signaling pathway, fructose metabolism, and mannose metabolism in both S. aureus- and E. coli-induced sepsis." (PMID 31093495, 2019). "Serum levels of TNF-α and IL-6 are indicative of the immune system activation during sepsis." (PMID 31747882, 2019). "Elevated levels of TNFα have also been documented in foals with presumed “septicemia”." (PMID 30931316, 2019). "This information confirms that TNF-α could be incorporated into an anti-inflammatory strategy and act as a factor of fundamental importance for the treatment of sepsis and the inhibition of these cytokines." (PMID 30949497, 2019). "Additionally, the excessive expression of inflammatory cytokines (TNF-α and IL-6) during sepsis leads to tissue and cell damage." (PMID 30779706, 2019). "The disruption of TLR signaling pathway induced by live virulent E. coli and E. coli-derived LPS in pigs by CD14 neutralization antibodies resulted in decreased levels of pro-inflammatory cytokines IL-1β, IL-6, IL-8, and TNF-α, and lower granulocyte activation in a pig model of sepsis." (PMID 31847111, 2019). "Cytokines TNF-α and IL-1 are the most extensively studied pro-inflammatory mediators in sepsis." (PMID 31281814, 2019). "In animal models of polymicrobial sepsis, neonates tend to show lower absolute plasma concentrations of TNF-α, IL-1α/β, IL-12, GM-CSF, CCL5 (RANTES), macrophage inflammatory protein (MIP)-1β and IFN-γ as compared to adults, when challenged with an equally-lethal dose of “cecal slurry”." (PMID 31456998, 2019). "Interestingly, only Olv and Omg decreased the sepsis-induced secretion of the inflammatory cytokines, TNF-α, IL-6, and IL-1β and stimulated the secretion of the anti-inflammatory cytokine, IL-10." (PMID 31333903, 2019). "On the contrary, TNF-α neutralization reduced mortality in an LPS-induced sepsis model." (PMID 31480519, 2019). "For the proinflammatory cytokines, the levels of IL-1β, IL-2, IL-6, and TNF-α were elevated in the early sepsis phase (2 h), but most other proinflammatory cytokines, including IL-12, IL-15, IL-17, and IFN-γ, showed significant elevation in the late sepsis phase (24–48 h)." (PMID 31354717, 2019). "This neuroprotective effect of clenbuterol in the memory impairment induced by sepsis was accompanied by polarizing microglia toward an anti-inflammatory phenotype, reducing proinflammatory cytokines including IL-1β and TNF-α, and reversing synaptic abnormalities." (PMID 31354429, 2019). "Notably, APC has been shown to directly inhibit activation and migration of monocytes as well as TNF-α production of macrophages, thereby reducing endotoxemia and sepsis mortality." (PMID 30971954, 2019). "To further determine whether GSS inhibits sepsis-induced lung inflammation in vivo, we use ELISA analysis to check the changes of TNF-α and IL-6 in the lung tissue and serum, respectively." (PMID 32082076, 2019). "This is in keeping with previous studies of major surgery and suggests that IL-6 may be the main driver of the postoperative response while TNF-α is involved in the inflammatory response to sepsis." (PMID 29454501, 2019).
Sepsis (continued). "In addition, our previous study analyzing correlation between PPAR polymorphisms and sepsis risk found that rs10865710G allele carriers had higher sepsis morbidity, MOD scores, and LPS-induced TNF-α production, which was confirmed in the present study." (PMID 31888703, 2019). "Treatment re-sensitizes both neutrophils and macrophages to LPS, with treated cells releasing significantly higher levels of pro inflammatory cytokines including TNF-α, IL-6, and IL-8, all of which are released at significantly lower levels in many patients during the later stages of sepsis." (PMID 31281814, 2019). "Concentrations of IL6 and TNFα are typically elevated during infections and sepsis." (PMID 31121841, 2019). "Inflammatory cytokines such as TNF-α and IL-6 result in cardiac dysfunction in sepsis." (PMID 31315617, 2019). "This might be due to that lnc‐THRIL facilitated inflammatory response by facilitating TNF‐α and other inflammatory markers, hence, aggravated the disease severity and increased the risk of ARDS, which eventually led to poor survival in sepsis patients." (PMID 31257645, 2019). "Also, administration of IL-10 after induction of sepsis was found to decrease lethality in mice through suppressing the elevation of systemic TNF-α." (PMID 31370884, 2019). "Additionally, it has been found that serum levels of IL-1β and TNFα are only 45%–50% lower in healthy patients than those hospitalized with sepsis." (PMID 30897777, 2019). "TNF-α is a pro-inflammatory cytokine that has been widely studied in the pathophysiology of sepsis." (PMID 31671729, 2019). "During sepsis, macrophages are activated by various stimuli, such as gram-negative bacteria and LPS, resulting in transcriptional upregulation of inflammatory genes, including inducible nitric oxide synthase (iNOS), IL-1β, and TNF-α." (PMID 31847346, 2019). "We previously reported that treatment of mice with MTA before infection with a lethal dose of S. Typhimurium resulted in reduced production of sepsis-related cytokines (interleukin-6 [IL-6] and tumor necrosis factor alpha [TNF-α]) and modestly prolonged survival." (PMID 29866910, 2018). "Furthermore, pharmacological targeting by antibodies to histones or by activated protein C (APC) reduced the mortality of mice in LPS, TNF or CLP models of sepsis." (PMID 29728738, 2018). "Indeed, TNF represents an active and attractive objective for drug development despite the initial skepticism because of the failure of anti-TNF drugs in sepsis patients." (PMID 29751683, 2018). "However, during established infections, excessive levels of TNF participate to the dysregulated immune responses that contribute to the pathogenesis of sepsis." (PMID 30050534, 2018). "Furthermore, RelB accumulated at the TNF-α promoter region in endotoxin-tolerant sepsis blood leukocytes." (PMID 30533222, 2018). "Interestingly, PLD1 mediates TNF-α regulation via MEK1 and ERK phosphorylation leading to reduced Egr1 expression after LPS-induced sepsis in PLD1 deficient mice." (PMID 30555342, 2018). "By combining phenotypic analysis of exhaustion markers with functional analysis of cytokine production, we found that PD-1+ CD4+ cells in cancer hosts failed to make any cytokines following CLP, while the 2B4+ PD-1lo cells in cancer mice secreted increased TNF during sepsis." (PMID 29338031, 2018). "Another argument that therapy aimed at inhibition of the immune response should not be discarded as of yet comes from a meta-analysis of 17 randomized controlled trials (almost 9,000 patients) evaluating the effects of anti-tumor necrosis factor alpha (TNF-α) therapy on mortality in severe sepsis." (PMID 30233566, 2018). "Moreover, high TNF-α and IL-1 circulating levels are considered as the hallmarks of a cytokine storm and their role in sepsis pathophysiology has been largely investigated." (PMID 29974037, 2018).
Sepsis (continued). "While tumor necrosis factor-alpha (TNF-alpha) plays a pivotal role in the onset of adult sepsis, interleukin- (IL-) 6 and IL-8 represent the cytokines mainly involved in the initiation of the sepsis cascade in the newborn." (PMID 30174784, 2018). "The levels of TNF-α, IL-6 and IL-10 were significantly higher in the miR-31 mimic group (all p < 0.05) while significantly lower levels were observed in the miR-31 inhibitor group when compared with the sepsis group (all p < 0.05)." (PMID 30340459, 2018). "When given beforehand, whether the event is delirium or sepsis, TNF's effects can be nipped in the bud." (PMID 29725287, 2018). "Therefore, we conclude that in contrast to the situation in sepsis, where LPS and TNF-α are relevant, alterations of cAMP levels as well as Rac1 activity are less important in anaphylaxis." (PMID 30185878, 2018). "Tissue injury after trauma or infection results in an increased expression of pro-inflammatory cytokines, such as tumor necrosis factor alpha (TNF-α) and interleukin (IL)-6, both of which play a central role in the process of trauma and sepsis-associated cardiac dysfunction." (PMID 29616016, 2018). "Thus, fenoldopam can inhibit TNF production in splenocytes at high glucose concentrations, and can provide therapeutic advantages for treating diabetic patients with sepsis." (PMID 29780390, 2018). "Comparison of LPS stimulated NFATc3−/− and WT BMDM gene expression indicated distinct down regulation of LPS induced CCR2 and TNFα in NFATc3−/− macrophages, suggesting that NFATc3 regulates macrophage gene expression thereby regulates pathogenesis of sepsis induced-ALI." (PMID 29535830, 2018). "We found that, in a previous study, exogenous Cit alleviated the release of proinflammatory cytokines (TNF-α, IL-1β, and IL-6) in early sepsis and increased the release of late-stage anti-inflammatory cytokines (IL-4 and IL-10) to alleviate the inflammatory response of septic rats." (PMID 30498752, 2018). "In addition, the inhibition of lipogenesis or the increase in lipid oxidation reduces levels of free fatty acids, TNF-α, and IL-6, and reduces liver injury improving survival in sepsis." (PMID 29760707, 2018). "ROS and TNF-α contribute to apoptosis, and apoptosis is a key process in sepsis." (PMID 30249753, 2018). "As sepsis involves the presence of a pathogen, the inability to control the infection when TNF signaling is abrogated might account for the failure seen in these clinical trials." (PMID 29751683, 2018). "Several polymorphisms have been identified at different positions of the TNF-α promoter region in various infectious and inflammatory diseases, mainly focusing on the promoter single nucleotide polymorphism TNF-α-308 G/A in sepsis." (PMID 28840846, 2018). "Therefore, in sepsis, LPS in kidney tissues mediated apoptosis by TNF/TNFR1, and apoptosis of epithelial cells was an important pathological pathway for kidney injury." (PMID 29980183, 2018). "Sepsis is one of the most common causes of ALI, with LPS being the most important biological mediator as they induce the secretion of inflammatory cytokines, such as TNF-α, IL-1β, and IL-6 in response to bacterial toxins." (PMID 30083155, 2018). "Here we identified PLD1 as regulator of TNF-α expression and release upon experimental sepsis." (PMID 29968773, 2018). "Previous studies have shown that vagus nerve stimulation using electrical or pharmacological approaches in models of endotoxemia and sepsis results in suppression of LPS-induced TNFα production in splenic macrophages through activation of the cholinergic anti-inflammatory pathway." (PMID 30237803, 2018). "IL-6 governs the production of acute phase proteins, and together with IL-1β, IL-12/23/p40, and TNF-α, are termed proinflammatory cytokines and are induced in intestinal mucosa during sepsis, and in enterocytes after in vitro treatment with endotoxin and other proinflammatory cytokines." (PMID 29491864, 2018).
Sepsis (continued). "H9C2 cells were treated with LPS to induce sepsis, and miR-146a overexpression significantly increased the cell viability, reduced the apoptosis and ROS level, and attenuated the release of proinflammatory cytokines including TNF-α and IL-1β." (PMID 30224945, 2018). "Significant improvement in mortality, lung function (attenuated capillary leak), and local and systemic inflammation (prevention of the increase of MCP-1 and TNFα) in a mouse model of severe sepsis-induced ALI after therapeutical HSP90 inhibition were observed." (PMID 29728738, 2018). "Necroptosis-promoting cytokines, including IFNα/β and TNFα, are induced by numerous disease states, including infection, as well as clinical protocols, such as radiation and BM transplantation, and are a potential prognostic biomarker in patients with sepsis." (PMID 30080899, 2018). "In contrast, our data suggest that TNF antagonism, which was tested in clinical trials in sepsis and failed, could be revisited in the context of sepsis with pre-existing malignancy." (PMID 29338031, 2018). "The Lethe lncRNA is involvedplay a role both in sepsis and in MetS in NF-kB regulation, and is co-induced with interleukin (IL)-1β and tumor necrosis factor (TNF)α, and downregulated by high-glucose environment, where it exacerbates the inflammatory cellular profile." (PMID 29922126, 2018). "Two initial molecules in sepsis that need further exploration are TNF-α and interleukin-1 (IL-1)." (PMID 28840846, 2018). "PLD1 is crucial for TNF-α mediated inflammation after MI and LPS-induced sepsis in mice." (PMID 30555342, 2018). "XBJ normalized TNFα and IL-6 production in rodent sepsis models." (PMID 30618740, 2018). "Therefore, we evaluated the effects of pilloin on TNF-α and IL-6 levels in an LPS-induced sepsis model." (PMID 30513815, 2018). "Thus, in the present study, the inhibition of let-7a-5p resulted in significantly increased concentrations of TNF-α, IL-1β, IL-6, and iNOS and decreased hepatic function in mice with sepsis." (PMID 29599918, 2018). "TNF-α signaling mediates many of the systemic inflammatory consequences of sepsis." (PMID 30123776, 2018). "TNF-α is the most frequently studied cytokine with regards to the pathophysiology of sepsis." (PMID 30142934, 2018). "Our results indicate that glucose increases TNF production in splenocytes showing that hyperglycemia directly affects the inflammatory responses to bacterial endotoxin and contributes to systemic inflammation in sepsis." (PMID 29780390, 2018). "Publicly available transcription data have likewise been used to generate predictive signatures for TB, systemic sclerosis, transplantation allograft survival, sepsis, anti-TNF (anti-tumor necrosis factor) treatment response in inflammatory bowel disease (IBD) patients, and many other conditions." (PMID 30266097, 2018). "In patients with IBD who had received low accumulated dosages of anti-TNF-α agents, risks for pneumonia (HR = 2.2, 95% CI: 1.1–4.5), urinary tract infection (HR = 2.4, 95% CI: 1.3–4.5), sepsis (HR = 4.0, 95% CI: 2.6–6.1), and abdominal abscess (HR = 6.0, 95% CI: 3.4–10.5) increased." (PMID 30373275, 2018). "However, treatment of sepsis based on anti-tumor necrosis factor (TNF)-α antibody and interleukin (IL)-1 receptor antagonist did not demonstrate any clinical benefit." (PMID 29520271, 2018). "Powerful pro-inflammatory mediators, especially tumor necrosis factor-α (TNF-α), interleukin (IL)-6, IL-1 and IL-8 are produced by endothelial and epithelial cells as well as neutrophils, monocytes, macrophages and lymphocytes at the early onset of sepsis." (PMID 30563044, 2018). "Moreover, IL-1 and TNF-α are also known as soluble cardiodepressant factors in patients with sepsis." (PMID 30619885, 2018). "Some studies show that circulating TNF-α may contribute to hepatocellular dysfunction in early sepsis and that TNF-α concentrations in plasma are a predictor of mortality in septic mice." (PMID 28105603, 2017).
Sepsis (continued). "Activation of the innate immune system by sepsis produces pro-inflammatory cytokines (TNFα, IL-1β and IL-6) that may trigger muscle wasting." (PMID 28883493, 2017). "Our present study differed from previous investigations using the animal models induced by stress, LPS or sepsis, where we directly determined hippocampal cytosol protein levels of IL-6, IL-1β, and TNF-α by using acute and chronic ketamine administration models." (PMID 28373844, 2017). "The failure of anti-TNF-α- or IL-1β-based therapies to decrease the death toll in sepsis patients has generated doubts as to whether cytokine-based treatments can be effective." (PMID 28533774, 2017). "We determined the plasma concentrations of TNF-α, IL-6 and IL-1β to determine whether MCP-1 gene polymorphisms had any effect on the production of these related cytokines in the sepsis and control groups." (PMID 28472164, 2017). "Apart from TNF-α, it also has been documented that other pro-inflammatory cytokines such as IL-6 could increase significantly in sepsis patients." (PMID 29207683, 2017). "In addition to the measurement of IL-1Ra, the serum levels of TNF-α and IL-1β, two key proinflammatory cytokines involved in the LPS-sepsis, were also quantified." (PMID 28383060, 2017). "Furthermore, the MCP-1 rs1024611 AG/GG and rs2857656 GC/CC genotype carriers exhibited significantly higher concentrations of TNF-α and IL-6 compared with the rs1024611 AA and rs2857656 GG genotype carriers among the sepsis patients." (PMID 28472164, 2017). "Therefore, in this study, the cardiovascular protection of oestrogen during sepsis can be mediated via the inhibitory effects on cellular NF‐κB signalling activation, leading to TNF‐α and IL‐6 release and cardiac iNOS induction." (PMID 28714586, 2017). "All concentrations of TNF-α improved cell migration both in healthy sera and sepsis sera wounds." (PMID 28086962, 2017). "Therefore, we combined CLP-induced sepsis with intermittent blood sampling monitoring the endogenous production of IL-6, TNF-α and IL-10 in rats over 72 h." (PMID 29204105, 2017). "In addition, 20 patients with post-surgical inflammation, 20 patients with sepsis or septic shock were included and TNFα was determined following ex vivo stimulation of whole blood with 500 pg/mL LPS." (PMID 28771573, 2017). "The over-production of TNF-α in LPS-induced RAW264.7 cells may cause tissue damage, even leading to sepsis and shock." (PMID 28333094, 2017). "Importantly, the plasma concentrations of TNF-α and IL-6 were significantly increased in sepsis patients with rs1024611 AG/GG or rs2857656 GC/CC genotypes, accompanied by an upregulation of MCP-1." (PMID 28472164, 2017). "In contrast, IL-10-mediated control of excessive production of TNF-α and IL-6, which drive the pathological effects of the ‘cytokine storm’ found in patients with sepsis and septic shock may on the other hand be beneficial." (PMID 28216665, 2017). "On the one hand, in some studies it was found that SP could play a role in the inflammatory response to sepsis by the release of pro-inflammatory cytokines as interleukin (IL)-1, IL-6, and tumor necrosis factor (TNF)-α." (PMID 28714876, 2017). "The therapeutic potential of the mutant peptides in the clinical treatment of LPS-induced sepsis was reflected their ability to bind LPS directly and inhibit LPS-induced TNF-α and IL-6 release both in vitro and in vivo, promoting the survival rate of mice with endotoxemia." (PMID 28054660, 2017). "A total of 16 studies involving 2,850 patients with sepsis, of whom 2,064 survived through the end of the study and 786 did not, examined the potential relationship between the TNF-α −308 A/G polymorphism and sepsis-related mortality." (PMID 29212277, 2017). "The high-susceptibility of sepsis-surviving mice to L. pneumophila infection was not accompanied by changes in the production of pro-inflammatory cytokines, such as TNF and IL-6." (PMID 28374774, 2017).